CYP2C18 (cytochrome P450 family 2 subfamily C member 18)
Description:
A cytochrome P450 monooxygenase involved in retinoid metabolism. Hydroxylates all trans-retinoic acid (atRA) to 4-hydroxyretinoate and may modulate atRA signaling and clearance. Mechanistically, uses molecular oxygen inserting one oxygen atom into a substrate, and reducing the second into a water molecule, with two electrons provided by NADPH via cytochrome P450 reductase (CPR; NADPH-ferrihemoprotein reductase).
Synonyms: P450IIC17; CPCI; CYP2C; CYP2C17; P450-6B/29C
Tractability: Small molecule: it belongs to a druggable protein family. Antibody: its Gene Ontology location is reachable by antibodies, with high confidence; UniProt places it where antibodies can reach, with medium confidence; UniProt predicts a signal peptide or a membrane-spanning region. PROTAC: its protein half-life has been measured; a small molecule that binds it is known.
Target class: Enzyme; Cytochrome P450 family 2; Cytochrome P450 family 2C; Cytochrome P450 2C18; Cytochrome P450
Gene: Protein-coding gene on chromosome 10 (94,682,944 to 94,736,190, forward strand). Ensembl gene ENSG00000108242.
Subcellular location: Endoplasmic reticulum membrane; Microsome membrane
Subcellular location (Human Protein Atlas): Vesicles; Plasma membrane
Pathways (Reactome):
Metabolism: Xenobiotics
Gene Ontology:
Molecular function: oxidoreductase activity, acting on paired donors, with incorporation or reduction of molecular oxygen, reduced flavin or flavoprotein as one donor, and incorporation of one atom of oxygen; retinoic acid 4-hydroxylase activity; heme binding; monooxygenase activity; oxygen binding; arachidonate epoxygenase activity; iron ion binding; linoleic acid epoxygenase activity; oxidoreductase activity, acting on paired donors, with incorporation or reduction of molecular oxygen
Biological process: retinoic acid metabolic process; epoxygenase P450 pathway; xenobiotic catabolic process; xenobiotic metabolic process; monocarboxylic acid metabolic process; retinol metabolic process; terpenoid metabolic process
Cellular component: endoplasmic reticulum membrane; cytoplasm
Genetic constraint (gnomAD): Loss-of-function variants: 32 observed, 36.98 expected, observed/expected ratio (o/e) 0.87, 90% interval 0.65 to 1.16. The upper end of that interval is the gene's LOEUF score, 1.16, which puts it in group 5 of 6, group 1 being the genes least tolerant of losing a copy. Missense variants: 591 observed, 571.08 expected, observed/expected ratio (o/e) 1.03, 90% interval 0.97 to 1.11. Synonymous variants: 221 observed, 205.64 expected, observed/expected ratio (o/e) 1.07, 90% interval 0.96 to 1.2.
Homologues: Orthologues: rat Cyp2c24 (78% identical), rat Cyp2c11 (77% identical), mouse Cyp2c55 (76% identical), rat Cyp2c55 (75% identical). Paralogues in human: CYP2C9 (82% identical), CYP2C19 (81% identical), CYP2C8 (77% identical), CYP2E1 (57% identical), CYP2F1 (51% identical), CYP2A13 (50% identical), CYP2A6 (49% identical), CYP2A7 (48% identical), CYP2B6 (48% identical), CYP2S1 (44% identical), CYP2J2 (39% identical), CYP2D6 (39% identical), and 3 more.
Diseases named in the same sentence as CYP2C18 in open-access papers:
CYP2C18 is named in the same sentence as 15 diseases in open-access papers, as found by Europe PMC text mining. Sharing a sentence is not in itself a finding about the gene and the disease. The quoted sentences say what the papers report.
pancreatic cancer (2 papers, 2017 to 2022). "Although CYP2C18 was highly correlated with OS and upregulated in PAAD cell lines via qPCR, research on CYP2C18 was mostly concentrated in the gastrointestinal tract and liver, with relatively few studies in pancreatic cancer and lack of immunohistochemistry image in the HPA database." (PMID 36685915, 2022).
Cluster headache (1 paper, 2022). A type of headache characterized by repeated attacks of unilateral pain lasting 15 to 180 minutes and associated with local autonomic signs. "In addition, both GWAS and gene-based association analysis suggested CYP2C18 as a potential novel susceptibility gene for cluster headache." (PMID 36404298, 2022). "We identified three susceptibility loci, in CAPN2, MERTK, and SATB2, as well as one suggestive locus at CYP2C18/CYP2C19 at genome-wide level in patients with cluster headache in Taiwan." (PMID 36404298, 2022).
endometriosis (1 paper, 2025). The growth of functional endometrial tissue in anatomic sites outside the uterine body. "Statistically significant differences were observed in the expression levels of six hub genes (ACSL4, CYP2C18, CYP2C9, HSD17B3, HSDL2, and PTGS2) between the Endometriosis and Control groups of the combined GEO datasets (p < 0.001)." (PMID 40313549, 2025).
Histiocytosis (1 paper, 2008). An excessive number of histiocytes (tissue macrophages). "Minimal perivascular infiltration of neutrophils was found on microscopic examination in the epididymal fat in one tg-CYP2C18&19 male and minimal alveolar histiocytosis was present in one tg-CYP2C18&19 female." (PMID 19038035, 2008).
ulcerative colitis (1 paper, 2021). An inflammatory bowel disease involving the mucosal surface of the large intestine and rectum. "Finally, by combining these expression features with genetic resources, we identified some candidate genes with potential to serve as novel markers of ulcerative colitis, such as CYP2C18." (PMID 34211502, 2021).
cancer (5 papers, 2017 to 2022). A tumor composed of atypical neoplastic, often pleomorphic cells that invade other tissues. "CYP2C18 belongs to the cytochrome P450 2C subfamily, which has a strong risk of cancer susceptibility." (PMID 36685915, 2022). "CYP2C18 belongs to cytochrome P450 2C subfamily, which is involved in cancer susceptibility risk." (PMID 28099906, 2017). "However, the correlation between CYP2C18 and cancer risk has not been reported." (PMID 35127473, 2021). "In chemical carcinogenesis metabolism, benzo[a]pyrene can be metabolized by CYP2C8, CYP2C9, CYP2C18, and CYP2C19, and then finally transformed into the DNA adduct (+)‐trans‐BPDE‐N2‐dG, which has been shown to promote cancers of the skin, lung, and stomach." (PMID 29479826, 2018). "Moreover, CYP2C9 is reportedly associated with the risk of colorectal cancer 16, while CYP2C18 was found to have no contribution to cancer risk 11 and CYP2C19 has been associated with peptic ulcer disease 17, colorectal adenoma recurrence 18, breast cancer 19, and cardiovascular diseases." (PMID 29479826, 2018).
CYP2C18 also shares sentences with these, for which no sentence is quoted: breast carcinoma (1 paper); Cirrhosis (1); Follicular Cyst (1); hepatocellular carcinoma (1); inflammatory bowel disease (1); Obesity (1); pancreatic adenocarcinoma (1); salpingitis (1); tumor (1).